ABCA1 (ATP binding cassette subfamily A member 1)
Diseases named in the same sentence as ABCA1 in open-access papers (continued):
Sharing a sentence is not in itself a finding about the gene and the disease.
cancer (continued). "Interestingly, ABCA1 and ETV1 are upregulated genes by embigin overexpression in both cancer and metabolic disease cluster." (PMID 30041429, 2018). "Besides the fact that the ABCA subfamily’s role as lipid transporters, the specific functions of ABCA1, ABCA13, and ABCD4 in cancer and specifically GBM are relatively unknown, which might warrant closer and more in-depth studies." (PMID 39861164, 2025). "However, we observed a negative correlation between cancer-associated fibroblast infiltration in TGCT and ABCA1 expression." (PMID 40297807, 2025). "However, the mutations in ABCB1, ABCA1, ABCC1 and ABCG2 did not affect overall cancer survival rates as determined by log-rank tests (all P-values < 0.05)." (PMID 34541464, 2020). "In cancer cells simvastatin did not markedly affect ABCA1 expression." (PMID 22761797, 2012). "Both normal and cancer cells increase the production of effectors that ensure the synthesis and uptake of cholesterol under depletion, but cancer cells do not express the major exporter of cholesterol, ABCA1 even in the abundance of LDL." (PMID 22761797, 2012). "Indeed, we found that reducing the level of ABCA1 could suppress serous EOC growth in two-dimensional as well as three-dimensional cell culture and also hindered their migration, a key process required for cancer spread." (PMID 35454786, 2022). "Consistent with the in vivo evidence that fasting stimulates ABCG1, but not ABCA1 expression, we observed that in vitro, cholesterol efflux from both HCT116 and MCF7 cancer cells only increased under FMCC when HDLs, but not ApoA-I were used as acceptors." (PMID 37907500, 2023). "Using the datasets in The Cancer Genome Atlas and Gene Expression Omnibus, we found upregulated ABC transporters that either negatively impacted survival in univariate analyses (ABCA1, ABCA13, ABCB9, ABCD4) or were independent negative prognosis factors for patients with GBM (ABCA13, ABCB9)." (PMID 39861164, 2025). "Summarizing, although there is no conclusive evidence that ABCA1 is involved in the carcinogenesis process, unlike other members of the ABC transporter family, it seems to play an important role in proliferation and survival of cancer cells." (PMID 33562440, 2021). "ABCA1, an ABC transporter, but not ABCB1, ABCC1 or ABCC2, might be involved in the anti-cancer drug resistance observed in DU145 cells stably overexpressing embigin." (PMID 30041429, 2018). "The molecular circuitry TFEB/SREPB2/cholesterol homeostasis genes is not cell type or cancer type-specific: indeed, THP-1 macrophages exposed to reactive oxygen species had increased nuclear translocation of TFEB, increased endogenous synthesis of cholesterol and efflux via ABCA1." (PMID 39107857, 2024).
cardiovascular disease (44 papers, 2008 to 2025). "We described three patients with mutations in CETP, LCAT, and ABCA1, demonstrating the clinical presentation and risk for cardiovascular disease." (PMID 40476138, 2025). "Defects in ABCA1 can lead to intracellular cholesterol accumulation, thereby increasing the risk of cardiovascular disease." (PMID 40808841, 2025). "In mice, Abca1 deficiency was found to accumulate cholesteryl esters in tissues, increasing the risk of cardiovascular disease." (PMID 40003065, 2025). "Accordingly, patients with Tangier Disease, who carry loss-of-function mutations in ABCA1, exhibit an elevated risk of cardiovascular disease mortality." (PMID 40786884, 2025). "Literature data about ABCA1 concern primarily cardiovascular disease and variants classified as benign due to their relatively high frequency in the population are often associated with a certain level of risk for these diseases." (PMID 36570531, 2022). "Here, we outline several investigations that provide novel insights into ABCA1 glycosylation modification and the risk of cardiovascular diseases." (PMID 35743794, 2022). "Genome-wide association studies (GWAS) have identified many functional SNPs located in ABCA1 that are associated with cardiovascular diseases." (PMID 35743794, 2022). "Meanwhile, carriers of the loss-of-function ABCA1 gene are often accompanied by decreased expression of ABCA1 and an increased risk of cardiovascular diseases." (PMID 35743794, 2022). "Further studies are needed to explore the impact of ABCA1 polymorphisms on plasma lipid profiles and cardiovascular diseases." (PMID 35743794, 2022). "In spite of the many studies that have identified that ABCA1 PTMs are involved in a variety of pathophysiological processes, few studies show the direct associations between the PTMs of ABCA1 in cardiovascular diseases." (PMID 35743794, 2022). "It has been reported that ABCA1 mutations can decrease plasma high-density lipoprotein levels, augment the risk of type 2 diabetes, and aggravate cardiovascular disease." (PMID 32774146, 2020). "The rs2230806 is the most common polymorphism of ABCA1; the possible role of rs2230806 in cardiovascular diseases is still debatable as numerous studies have reported divergent results." (PMID 26936456, 2016). "Polymorphisms in ABCA1 are one of the strongest factors affecting plasma levels of high density lipoprotein and risk of cardiovascular disease." (PMID 18802465, 2008). "Considering that ABCA1 is most abundant in macrophages and its function is to maintain cholesterol homeostasis, much more research is needed to explore the underlying molecular mechanism by which ABCA1 modulates cardiovascular diseases through macrophages." (PMID 35743794, 2022). "Overall, these results suggest that both in utero and postnatal environments might modulate the ABCA1 epigenetic profile and trigger a long-term susceptibility to cardiovascular diseases including PAH." (PMID 28881789, 2017). "Low levels of ABCA1/G1 in monocytes/macrophages and reduced plasma HDL levels are associated with an increased risk of cardiovascular diseases." (PMID 40786884, 2025). "ATP-binding cassette A1 (ABCA1) is a membrane protein, which exports excess cellular cholesterol to generate HDL to reduce the risk of the onset of cardiovascular diseases (CVD)." (PMID 36816300, 2023). "During lipid metabolism in cardiovascular disease, the vascular transcriptional machinery of fundamental genes such as ABCA1 is altered." (PMID 36767748, 2023). "ABCA1 plays a pivotal role in maintaining cholesterol homeostasis and has biomedical significance in protecting against cardiovascular disease." (PMID 35743794, 2022). "Epidemiological studies have shown that mutations and loss-of-function in ABCA1 significantly decrease HDL-C levels and accelerate cardiovascular diseases risk." (PMID 35743794, 2022).
cardiovascular disease (continued). "These initial data led us to explore the potential correlation between miR-199a-5p with one of the most widely studied genes in the context of cardiovascular disease and cholesterol metabolism, ABCA1." (PMID 36407436, 2022). "The role of the ATP binding cassette transporter A1 (ABCA1) in maintaining cellular lipid homeostasis in cardiovascular disease is well established." (PMID 32977800, 2020). "ABCA1, which is involved in the reverse cholesterol transport pathway, has been considered as a new therapeutic target for cardiovascular disease." (PMID 30233285, 2018). "The efflux of cholesterol from macrophages or tissues by ABCA1 is considered beneficial in the prevention of cardiovascular disease." (PMID 26729088, 2015). "In addition, oxidative modifications of HDL in cardiovascular disease patients hinder apolipoproteins from efficiently removing cellular cholesterol via the ABCA1 pathway." (PMID 38673936, 2024). "ABCA1 was identified as the disease-causing gene for Tangier disease, a rare genetic disorder that exhibits a severe reduction in plasma high-density lipoprotein (HDL) level and a high incidence of premature cardiovascular disease (CVD)." (PMID 36816300, 2023). "In this review, we used cardiovascular disease; inflammation; polymorphism; post-translational modification (PTM); transcription regulation; ATP binding cassette transporter 1 (ABCA1); cholesterol; high density lipoprotein cholesterol (HDL-C) as keywords to search interested literatures." (PMID 35743794, 2022). "This review summarizes the current knowledge on ABCA1 transcription regulation mechanism, gene polymorphism, post-translational modification, and its role in the development of diverse cardiovascular diseases, highlighting ABCA1 as a potential therapeutic target for cardiovascular diseases." (PMID 35743794, 2022). "Determining how ABCA1 interacts with these inflammation pathways in cardiovascular diseases may ultimately uncover novel methods applied in cardiovascular disease therapy." (PMID 35743794, 2022). "At present, clinical staff shows a strong interest in ligands for LXRS and PPARs for the treatment of cardiovascular disease, and they are ligand-activated transcription factors that plays well-established roles in up-regulating transcription of ABCA1 and ABCG1." (PMID 24314261, 2013). "Whether MTX induced HY27 and ABCA1 expressions can protect against cardiovascular disease in patients with chronic inflammation through the facilitation of cholesterol export remains to be established." (PMID 21232092, 2011). "Thus, ABCA1 may prevent cardiovascular disease by inhibiting inflammation and maintaining lipid homeostasis." (PMID 35743794, 2022). "Therefore, it is critical to uncover the role of ABCA1 PTMs in cardiovascular diseases." (PMID 35743794, 2022). "High-density lipoprotein (HDL) cholesterol, protective against cardiovascular disease, facilitates reverse cholesterol transport via ABC transporters ABCA1 and ABCG1." (PMID 41416067, 2025). "Despite this evidence for the relationship of mutual regulation between ABCA1 expression and ANXA1 efflux, less is known regarding the potential role of this mutual regulatory effect in cardiovascular disease." (PMID 32894039, 2020). "TRAK2 has been reported as a novel regulator of ATP-binding cassette, sub-family A member 1 (ABCA1) expression, cholesterol efflux and HDL biogenesis, and therefore, TRAK2 may be an important target in the treatment of cardiovascular disorders." (PMID 36585686, 2022).
infection (42 papers, 2011 to 2026). The state of being infected such as from the introduction of a foreign agent such as serum, vaccine, antigenic substance or organism. "We observed that genes involved in cholesterol uptake (Lrp2) (denoted in grey across the figures) and biosynthesis (Aacs, Hmgcs1, Mvd, Dhcr24) were significantly upregulated during infection; while those implicated in efflux (Abca1, Abcg1) showed a marked downregulation." (PMID 37871034, 2023). "We showed that ABCA1 was upregulated on the macrophage cell-surface following infection with pathogenic mycobacteria and knockdown of ABCA1 resulted in increased mycobacterial survival within macrophages, suggesting that it may be a novel mycobacterial host-restriction factor." (PMID 27462310, 2016). "Since Nef down-regulates ABCA1 function through a post-translational mechanism, we also examined ABCA1 protein abundance 5-wk post infection." (PMID 39532531, 2025). "Changes in the expression of the LOX, ABCA1 and CD36 genes in the CETP mice indicate a possible association between lipid metabolism and the response to infection." (PMID 38966642, 2024). "Silencing the SREBP2 and ABCA1 genes significantly reduced SARS-CoV-2pp infection in Huh7 cells by 43% and 62%, respectively." (PMID 36014919, 2022). "Similar results were observed in human fibroblasts infected with CMV, where infection increased the efflux of cellular cholesterol despite reducing the abundance of the ATP-binding cassette transporter 1 (ABCA1)." (PMID 35883666, 2022). "IFNγ-induced decrease in Fasn and Fads2 expression correlated with reduced Abca1 and Dhcr24 transcript levels after 6 hr of infection, suggesting that IFNγ prevents Mtb-induced stimulation of FA biosynthesis through downregulation of LXR and SREBP1 activity." (PMID 34951591, 2021). "We found that during the first hours of infection of Mo-DC there is a change in the transcription of genes involved in cholesterol biosynthesis and export (ABCA1 and ApoA1) that would result in an increase in the intracellular IPP pool." (PMID 34381163, 2021). "The CD38+/CD14+ cells were the main cell population that expressed high levels of ABCA1 after infection." (PMID 32544188, 2020). "CD14, CD38, and Abca1 “triple positive” (TP) cells had not only the highest infection rates and bacterial loads, but also a strong interferon-γ signature and nitric oxide synthetase-2 production indicating recognition by T cells." (PMID 32544188, 2020). "In contrast, expression of Abca1 showed a temporal increase during the course of infection, with a tendency toward upregulation on 4 DPI, which became significant on 6 DPI and continued to increase on 8 DPI." (PMID 30940698, 2019). "By upregulating miR-155 late in infection, MTb has the capacity to block cholesterol efflux, by downregulating ABCA1, thus, securing its cholesterol requirements inside the foam cells." (PMID 28228760, 2017). "Among the top proteins with higher abundance after infection were Sglt4 (glucose transporter, Log2FC 5.11), Abca1 (intracellular cholesterol transporter, Log2FC 4.92), and iNOS (inducible nitric acid synthases, Log2FC 4.89)." (PMID 28988824, 2017). "We also observed that EZH2 infection reduced ABCA1 mRNA and protein levels in mouse peritoneal macrophages (MPM), aortas, hearts, livers and kidneys of apoE−/− mice." (PMID 27295295, 2016). "Stimulation of ABCA1 expression also efficiently inhibited infection of human hepatocytes in primary culture (the natural HCV target cell) and isolated human liver slices." (PMID 24646941, 2014). "Instead, inhibition of infection required ABCA1 over-expression and activation of its function during several hours." (PMID 24646941, 2014). "Up-regulation of ABCA1 decreased intracellular HCV RNA levels at 24 h post infection and significantly reduced the virus production." (PMID 24646941, 2014).
infection (continued). "ABCA1, which mediates the cholesterol flux and has been described to be overexpressed in cells that accumulate cholesterol, is also upregulated upon infection." (PMID 24812617, 2014). "MDMs were also infected with AD8 or ADnefmut virus along with infection of Ad-Cav-1 or Ad-GFP to determine the level of ABCA-1 expression." (PMID 23067370, 2012). "Abca1 was down-regulated in P. gingivalis-infected mice, with a greater reduction being observed during long-term infection." (PMID 21625524, 2011). "The gene expression profile of Abca1 showed a trend similar to that of the Lxrs, but a significant reduction was only observed during long-term infection." (PMID 21625524, 2011). "Together, the complementary effects of increased CEC and ABCA1 may reduce intracellular cholesterol levels during infection and contribute to IFNγ-independent Mtb control in RSTR." (PMID 39162406, 2024). "Additionally, ABCA1 gene expression has been shown to be upregulated after infection with Marek's disease virus (gallid alphaherpesvirus 2) in chicken fibroblasts." (PMID 37872508, 2023). "The enrichment analysis indicates that ABCA1 is mainly involved in immune regulation, such as cytokine metabolic process, cytokine production, cytokine binding, cytokine receptor activity, innate immune response, immune signaling pathway, and infection." (PMID 37749600, 2023). "However, at 24 hours post-infection (hpi), we observed a loss of SIRT6 recruitment, indicating a potential role of SIRT6 in regulating the expression of Abca1 and Abcg1 during the early stages of infection." (PMID 37871034, 2023). "Importantly, we did not detect induction of the APOA1 gene and only a modest induction of the ABCA1 gene following infection with the Δhly strain, suggesting that cytosol invasion was essential to augment the expression of these two genes." (PMID 34381163, 2021). "Further research is required to fully elucidate how ABCA1 and cholesterol homeostasis are involved in infections, and to establish whether ABCA1 can in fact be a therapeutic target." (PMID 33562440, 2021). "One was that CD14, CD38, and ABCA1 expression identify macrophages that are prone to infection." (PMID 32544188, 2020). "Importantly, we defined a population of myeloid cells, primarily CD11cHi monocyte-derived cells, which expressed high levels of CD14, CD38, and Abca1, and had the highest infection rates and bacterial loads." (PMID 32544188, 2020). "Thus, while it is clear that nga(G330D) infection induces P2X7-mediated membrane permeabilization and that ABCA-1 is implicated by most of the used inhibitors, the identity of the membrane passage remains to be determined." (PMID 31275321, 2019). "The highly significant modulation of these genes and in other genes related to channels/transporters such as Abca1 and Slc25a37 may be indicative of a metabolic shift in the host epithelium due to infection with C. rodentium." (PMID 29339782, 2018). "Importantly, at 14 DPI the abundance of the rate-limiting enzyme in the cholesterol biosynthetic pathway (hydroxymethyl-glutaryl-CoA reductase, Hmgcr) as well as Abca1, returned to pre-infection levels." (PMID 28988824, 2017). "We verified that infection of activated THP-1 cells, a human monocytic cell-line by pathogenic mycobacteria such as M. tuberculosis-H37Rv and M. abscessus also led to increased plasma-membrane expression of ABCA1." (PMID 27462310, 2016). "Increased abundance of ABCA1 was only evident at the terminal stage of the infection." (PMID 24280226, 2014). "Stimulation of ABCA1 expression with liver X receptor agonist or overexpression of heterologous ABCA1 reduced the conversion of prion protein into the pathological form upon infection." (PMID 24280226, 2014). "In summary, our findings suggest that during the early stages of infection, SIRT6 deacetylates H3K9, creating a platform for G9a-mediated demethylation of H3K9, ultimately leading to the transcriptional inactivation of Abca1 and Abcg1." (PMID 37871034, 2023).